ENSG00000287979 (novel transcript)
Gene: Long non-coding RNA gene on chromosome 1 (120,844,016 to 120,850,985, reverse strand). Ensembl gene ENSG00000287979.
Gene Ontology:
Molecular function: pre-mRNA 5'-splice site binding; triplet codon-amino acid adaptor activity
Biological process: mRNA 5'-splice site recognition; translation
Cellular component: U1 snRNP